CRP (C-reactive protein)
Diseases named in the same sentence as CRP in open-access papers (continued):
Sharing a sentence is not in itself a finding about the gene and the disease.
Sepsis (continued). "Compared with critically ill patients without sepsis, sepsis patients had higher PCT (28.11 ± 32.78 vs. 3.01 ± 5.77, p = 1.95 × 10−4), CRP (153.83 ± 78.66 vs. 74.05 ± 65.31, p = 4.19 × 10−4) and creatinine (154.95 ± 125.86 vs. 84.22 ± 98.58, p = .025) levels." (PMID 38270311, 2024). "This study found that diabetic individuals with UTIs and sepsis had substantially higher levels of CRP and WBC and a lower level of ALB compared to those without sepsis." (PMID 38771840, 2024). "Higher levels of PCT and CRP were produced after treatment with the CD52 monoclonal antibody alemtuzumab, similar to the sepsis brought on by Gram-negative bacteria." (PMID 39685604, 2024). "In that trial of 94 ICU-patients with sepsis, 49 were allocated to PCT and 45 to CRP measurements, without a control group." (PMID 39163362, 2024). "Conversely, a significant negative correlation was found between CRP levels and the ALB-CRP ratio (r = − 0.61), suggesting an inverse relationship in the context of sepsis progression." (PMID 38839818, 2024). "Many of the laboratory criteria, including increased inflammatory markers, such as CRP, procalcitonin, and ferritin, are not specific to MIS-N and can also occur in severe sepsis." (PMID 39867692, 2024). "Another study with the classic three patient groups—non-infection, infection, and sepsis—showed that the sensitivity was 83.0% for MDW (cut-off, 19.8), 69.7% for CRP (cut-off, 4.0), and 76.6% for PCT (cut-off, 0.05)." (PMID 39852198, 2024). "Threshold values were determined at 16mg/L for CRP and 2.8ng/L for PCT, providing a sensitivity of 100% for discerning between the absence of sepsis and confirmed diagnoses." (PMID 39193501, 2024). "Patients without sepsis admitted to the ICU, PCT and CRP were not always analyzed, unlike NEUT-RI, which was already available in the blood count." (PMID 37238265, 2023). "According to p values of Kaplan Meier’s analysis of CRP, PCT, and APACHE I they are not good predictors to separate sepsis from control." (PMID 37752563, 2023). "Compared with leucocytes (WBC), C-reactive protein (CRP), or procalcitonin (PCT), a secondary analysis revealed a better discrimination of sepsis from noninfectious systemic inflammatory processes induced by trauma or surgery based on soluble DLL1." (PMID 37298115, 2023). "Thus, in treated patients, CRP may no longer be a useful indicator of progression to more severe states, e.g., secondary bacterial infections, whereas SeptiScore values were not impacted, consistent with its original function as an indicator of sepsis." (PMID 36851633, 2023). "To address the expression of inflammatory factors in sepsis‐induced ALI, we tested the levels of CRP, PCT, and IL‐6 in patients with sepsis without ALI and patients with ALI." (PMID 37248197, 2023). "For the diagnosis of sepsis, NEUT-RI showed an AUC of >0.80 and a better negative predictive value than Procalcitonin (PCT) and C-reactive protein (CRP) (87.4% vs. 83.9% and 86.6%, p = 0.038)." (PMID 37238265, 2023). "For instance, the combination of PCT and CRP has shown promise in diagnosing BSI, particularly for sepsis, while IL-6 has proven useful in distinguishing sepsis from non-infectious systemic inflammatory response syndrome." (PMID 37986183, 2023). "Serum CRP levels were not significantly different between the control and CKD groups, regardless of sepsis induction." (PMID 36982713, 2023). "Although the CRP and PCT levels in the sepsis group were higher than those in the non-infection group, the medians were only slightly higher than the reference values." (PMID 36877734, 2023). "Sepsis criteria based on SIR.Sepsis criteria: pathogen detected in culture, fever > 38°C, C-Reactive protein > 1 mg/dl.Suspected sepsis: negative culture.Proven sepsis: positive culture." (PMID 37063664, 2023).
Sepsis (continued). "Procalcitonin (PCT) and C-reactive protein (CRP) are established tools mainly used to distinguish infectious from non-infectious conditions, but their prognostic properties in sepsis care have not been fully clarified." (PMID 36774492, 2023). "Of note, the sepsis biomarkers IL-6, PCT, presepsin and CRP are released from various other non-neutrophil immune cells." (PMID 37324133, 2023). "In the present study, the levels of CRP and PCT were increased in sepsis patients compared with non-sepsis patients." (PMID 35337261, 2022). "Previous studies have reported that C-reactive protein (CRP) and procalcitonin (PCT) are valuable prognostic factors, which are not satisfactory for predicting sepsis-related mortality." (PMID 35990041, 2022). "CRP and PCT levels were significantly higher in patients with sepsis, whereas WBC levels did not have significant difference between sepsis and non-sepsis group." (PMID 35550043, 2022). "Let-7d-3p expression significantly correlated to serum levels of CRP (r = 0.353, p = 0.032) but not PCT (r = 0.150, p = 0.376), two popular biomarkers of sepsis." (PMID 35187084, 2022). "A study of 233 patients in 200917 reported that plasma HBP levels of ≥ 15 ng/mL was a better indicator of severe sepsis (with or without septic shock) than PCT, IL-6, CRP, WBC and lactate." (PMID 35750778, 2022). "In accordance with the latest Dutch sepsis guidelines, PCT is not routinely measured in Dutch hospitals, since it has no additional value when compared with CRP." (PMID 35631080, 2022). "In the same study, increased plasma CRP levels and apoptotic cfDNA in plasma of non-survivors was also reported, an observation later confirmed in the ICU sepsis subjects by others." (PMID 36004363, 2022). "The levels of NLR, CRP, PCT, TBIL, AST, and Scr were higher in patients with severe bloodstream infection and sepsis than in the non-critical group, and the differences were statistically significant (P < 0.05)." (PMID 35345421, 2022). "Compared to the non-sepsis patients, sepsis patients had increased levels of PCT, CRP, and WBC count (all, p < 0.05)." (PMID 35337261, 2022). "The participants also wanted to reflect the increase in inflammatory markers, such as C-reactive protein (CRP) and procalcitonin (PCT), in sepsis, in addition to the WBC count, which is not very specific for sepsis." (PMID 36358234, 2022). "Other reports addressed the use of CRP and MDW for the prediction of sepsis, without showing increased accuracy." (PMID 36376821, 2022). "The study showed that the AUC values used to discriminate sepsis from non-sepsis were 0.88 for presepsin, 0.81 for PCT, and 0.65 for CRP." (PMID 34983420, 2022). "Considering the lack of informationon the relation between sPD1 and sepsis, the present study aimed to examine the sPD1 level in septic patients andevaluate its correlation with procalcitonin (PCT) and C-reactive protein (CRP) levels." (PMID 33650816, 2021). "This suggests that with WBC count and MDW, which can be obtained simultaneously, additional tests for CRP and PCT do not have advantages in sepsis diagnosis." (PMID 33857210, 2021). "Otherwise, there was no prognostic impact about IL‐18 in adult patients with sepsis, and IL‐18 was a biomarker better differentiating sepsis and septic shock status than PCT, CRP, and WBC." (PMID 33378581, 2021). "Heart rate, core temperature, C-reactive protein (CRP) values on admission, and length of stay (LOS) were increased compared to culture-negative sepsis." (PMID 34301181, 2021). "On the other hand, we found that PCT is an accurate marker for distinguishing sepsis from IWS, while CRP and WBC are not." (PMID 34344141, 2021). "PCT was found to be a more valuable marker than CRP and WBC for the discrimination of elderly patients with infected without sepsis and sepsis." (PMID 34344141, 2021). "IL-6 was significantly higher in sepsis than MIS-C (p < 0.01), while CRP and PCT were non-statistically different." (PMID 34869111, 2021).
Sepsis (continued). "C-reactive protein (CRP), procalcitonin (PCT), leukocytosis and thrombocytopenia are commonly described as sepsis biomarkers but are also often late, nonspecific and non-sensitive." (PMID 33498557, 2021). "Some inflammatory markers such as C-reactive protein (CRP) and procalcitonin (PCT) were not consistently able to predict the outcome of sepsis patients, and therefore better biomarkers are needed." (PMID 34578983, 2021). "We aimed to assess the usefulness of PCT, CRP, and WBC in distinguishing elderly patients infected with sepsis from infected without sepsis and those with no-infection." (PMID 34344141, 2021). "Even the well-known combination of the sepsis markers CRP and PCT did not improve the AUC (0.74; 95% CI, 0.70–0.79) to beyond that achieved by a single marker (CRP [AUC, 0.75; 95% CI, 0.71–0.78] or PCT [AUC, 0.76; 95% CI, 0.82–0.79])." (PMID 33857210, 2021). "Its diagnostic value is comparable to that of conventional markers, such as white blood cell (WBC), C-reactive protein (CRP) or procalcitonin (PCT), and can also be used to distinguish sepsis from non-infectious SIRS." (PMID 34943556, 2021). "In our study, low CRP levels, the absence of PMVG, sepsis and COPD were predictive for reversible PI." (PMID 34429069, 2021). "Overall, neutrophil and monocyte L-selectin were significantly predictive for sepsis and MOF with comparable AUCs to CRP, while neutrophil CD64 was predictive of MOF, but not sepsis." (PMID 34065206, 2021). "As expected, the CRP and PCT levels were also detected to be higher in the non-survivor group but we didn’t evaluate sepsis rate in this study." (PMID 33437244, 2021). "Although different screening tools and biomarkers, such as white cell count, neutrophil count, interleukin 6 (IL-6), CRP, and PCT, have been used for sepsis diagnosis, none of them is proven to be specific." (PMID 33292630, 2020). "As expected, sepsis patient with AKI exhibited significantly higher levels of serum creatinine and BUN, and inflammatory factors (calcitonin, neutrophils, and CRP) than sepsis patients without AKI." (PMID 33204323, 2020). "For discriminating sepsis from non-sepsis patients at the identified best cut-off, HBP had highest sensitivity, whereas CRP had the highest specificity, negative predictive value (NPV) and positive predictive value (PPV)." (PMID 32948801, 2020). "Its levels were evaluated, as usual, in blood samples obtained post mortem from cadavers divided in sepsis-related deaths group, local infections group, and non-sepsis ICU patients group, and compared to PCT, CRP, IL-6, and sTREM-1 levels." (PMID 33092081, 2020). "Unlike CRP, PCT levels assessed post mortem in pericardial fluid showed ranges similar to those found in blood samples, both in sepsis and control cases." (PMID 33092081, 2020). "Next to that, they had a higher sepsis severity (p < 0.001), a longer length of stay (LOS) (p < 0.001), and a higher C-reactive protein (CRP) level (p < 0.001) than those with culture-negative sepsis." (PMID 31113475, 2019). "Of these markers, CRP level and PCT level were also significantly different within the sepsis group in patients with bacteremia compared to sepsis patients without bacteremia." (PMID 30811475, 2019). "Role of CRP and WCC to identify those patients with sepsis, was more notable when patients who had surgery were divided according to the indication for surgery into sepsis and ischaemia." (PMID 31095593, 2019). "His CRP was 78 mg/l, ESR was 95 mm/first hour, and he was otherwise comfortable, showing no signs of sepsis beside the high grade fever." (PMID 30593283, 2018). "Commonly used biomarkers such as C-reactive protein (CRP), procalcitonin (PCT) and interleukin (IL)-6 were not adequately effective for predicting the severity and mortality of sepsis." (PMID 29282483, 2018).
Sepsis (continued). "Use of four biomarker strategies was evaluated based on hospital records: (i) >1 procalcitonin (PCT), (ii) 1 PCT, (iii) no PCT but ≥1 C-reactive protein (CRP) and/or lactate and (iv) no sepsis biomarkers." (PMID 30332466, 2018). "Laboratory tests, such as CRP and PCT, are not sufficient for the early diagnosis of sepsis with PROM." (PMID 30461611, 2018). "Some of the identified variables like PCT, CRP and IL-6 have been proposed before as markers for the differentiation between non-infectious SIRS and sepsis; others have not yet been described." (PMID 29544449, 2018). "Procalcitonin (PCT) and C-reactive Protein (CRP) are the biomarkers most commonly used, but have a limited ability to distinguish sepsis from other inflammatory and non-inflammatory states or to predict outcomes." (PMID 29891780, 2018). "In present study, plasma levels of CRP before age 12 hours were mostly low and predicted neither BPD nor sepsis." (PMID 28839172, 2017). "We compared the discriminative value between sepsis and non-infectious SIRS of MPO with CRP and leukocytes." (PMID 28916973, 2017). "We show that MPO had a similar discriminative value to CRP and that leukocytes did not differentiate between non-infectious SIRS and sepsis." (PMID 28916973, 2017). "CRP and MPO distinguished sepsis from non-infectious SIRS similarly (MPO: AUC 0.603 [95% confidence interval (CI) 0.538–0.668] versus CRP: AUC 0.636 [CI 0.572–0.700])." (PMID 28916973, 2017). "In conclusion, 1,25(OH)D but not 25(OH)D showed a minor discriminatory value for the prediction of bacteraemia that was inferior to CRP and PCT but both failed to predict sepsis and mortality in a prospective cohort of SIRS patients." (PMID 28079172, 2017). "While levels IL-8, IL-6, CRP, and PCT increased in sepsis compared to non-infective SIRS, only IL-6 positively correlated with sepsis severity." (PMID 29459855, 2017). "In our study, severity of sepsis estimated by Sequential Organ Failure Assessment (SOFA), number of leukocytes, lactate, C-reactive protein, procalcitonin and use of vasopressors did not relate to AKI recurrence." (PMID 28546861, 2017). "The relationship between CRP and PCT levels during FN episodes was investigated in our study, and it was found that CRP is not a sensitive marker of early infection in neutropenic patients, while PCT would be preferred in the early diagnosis of sepsis." (PMID 26377840, 2016). "Sepsis biomarkers, including PCT, IL-6 or CRP, did not help to explain discordant test results for BC and SF." (PMID 26986826, 2016). "The assessment of sepsis biomarkers showed that SIRS patients with detected pathogens in blood specimens had elevated PCT, LBP and CRP levels compared to non-bacteremic SIRS patients." (PMID 26986826, 2016). "Despite the availability of acute phase proteins, such as C-reactive protein (CRP), procalcitonin (PCT), and tumor necrosis factor, as sepsis markers, there is no ideal marker that can reliably differentiate between infected and non-infected patients." (PMID 27462492, 2016). "While WBCC, NeuC, Neu%, NLCR and EoC are far from being the indicators to distinguish sepsis from non-sepsis SIRS, the combinations of CRP, LymC and PLTC can be used to determine the likelihood of sepsis." (PMID 26863002, 2016). "Furthermore, ATP release on the plasma membrane was correlated with CD11b expression, WBC counts, neutrophil counts, and CRP levels in sepsis patients; thus, ATP release on the plasma membrane may reflect PMN activation and could potentially serve as an activation marker for sepsis." (PMID 27422255, 2016). "IL-6, CRP and TNF-α are common and sensitive but non-specific markers of inflammatory processes and increased concentrations are measured after trauma and in sepsis." (PMID 25609264, 2015). "In comparison with CRP, PCT seems to be a better marker to differentiate sepsis from non-infectious SIRS." (PMID 26357898, 2015).
Sepsis (continued). "At day 8 of ICU treatment, the diagnostic value of presepsin was evident for all different groups of sepsis severity (for example, diagnosis of at least sepsis, presepsin AUC = 0.82), whereas IL-6, PCT, WBC and CRP did not exceed an AUC ≥0.75." (PMID 25190134, 2014). "Levels of CRP and PCT on day 1 were significantly higher in patients with sepsis than in the no-sepsis-SIRS group." (PMID 24903083, 2014). "Recently, PCT, sTREM-1, CRP, and NT-pro-BNP cytokines were widely used to diagnose sepsis and reflect the severity, but the results were not the same." (PMID 24672147, 2014). "Therefore, CRP levels might not be increased further in patients with hepatic dysfunction, even under conditions of severe infection, such as septic shock or severe sepsis." (PMID 25407928, 2014). "In the case of sepsis patients, both PTX3 and high PCT seemed to be independent predictors of severe sepsis while CRP did not." (PMID 25530683, 2014). "PCT, CRP and WBC mostly failed to have any discriminative capacity for the different groups of sepsis severity at the different time points (AUCs <0.75)." (PMID 25190134, 2014). "IL-6 has the best discriminative power in sepsis and non-infectious SIRS, with sensitivity above 80% and specificity above 70%, which is higher than conventional inflammatory markers including CRP and TNF-α." (PMID 24341820, 2013). "Although one study claims that assessing serum CRP levels is not an adequate test for predicting sepsis related to mortality in ICU patients, other studies indicate that CRP is a proper predictor of mortality." (PMID 23171626, 2012). "In another study which looked at the relationship between CRP levels and mortality in sepsis patients within the first 24 hours after discharge from ICU, the mean CRP for non-survivors and survivors was 174 mg/L and 85.6 mg/L, respectively." (PMID 23171626, 2012). "Our results showed that WBC, IL-6, hs-CRP, and PCT values were higher among neonates with sepsis compared with those without sepsis either at the time of admission or at the end of the first day of life." (PMID 22708043, 2012). "Initial CRP was not a good mortality predictor in our study, but control CRP was found to be as significant as the SOFA score for predicting response to sepsis treatment and prognosis." (PMID 23171626, 2012). "The differences were not equal: median CRP and LBP levels in sepsis were about 1.5 to 2 times higher in sepsis, whereas median PCT and IL-6 were about 10 times higher in sepsis as compared to SIRS." (PMID 21687569, 2011). "During the first 5 days of sepsis, median plasma concentrations of LBP and CRP were even higher in S than in NS and did not discriminate both groups as assessed by ROC analysis (AUC<.55; data not shown)." (PMID 21901123, 2011). "In the second week of sepsis, we found a marked re-increase of LBP and CRP in the nonsurviving group most likely as part of an inflammatory response to a recurrent or unresolved infection." (PMID 21901123, 2011). "Given the lower costs and the long-term clinical experience with CRP measurements, we do not consider LBP as a useful biomarker for the monitoring of sepsis in patients post surgery." (PMID 21901123, 2011). "Levels of HMGB1, LBP, IL-6 and CRP in infected children without SIRS, with sepsis and with severe sepsis." (PMID 20158885, 2010). "CRP, leptin, IL-6 and TNF-α were compared among the following groups: sepsis group (n = 40), SIRS group (n = 34) and non-SIRS group (n = 32)." (PMID 20230641, 2010). "The main aim of this study was to compare the levels of HMGB1, LBP, IL-6 and CRP between infected children without systemic inflammatory response syndrome (SIRS) and children with sepsis of different severity levels." (PMID 20158885, 2010). "It is increasingly clear that none of the widely used biomarker for sepsis is perfect, but PCT performed much better than CRP and WBC count in chronic critically ill." (PMID 20028533, 2009).